RIPK1 (receptor interacting serine/threonine kinase 1)
Diseases named in the same sentence as RIPK1 in open-access papers (continued):
Sharing a sentence is not in itself a finding about the gene and the disease.
infection (continued). "In line with the defect of TNF-induced pS25 RIPK1 observed in IKKs or TAK1 inhibited conditions, we found that mimicking pS25 RIPK1 protected BMDMs from YopJ/P-dependent apoptosis following Y. enterocolitica (expressing YopP) and Y. pseudotuberculosis (expressing YopJ) infection." (PMID 30988283, 2019). "However, the protein level of RIPK1 was decreased upon infection while the amount of RIPK3 protein was increase at 3hpi and decreased at 12hpi when compared with mock-infected cells." (PMID 31165725, 2019). "The effect of HRV16 infection on RIPK1 cleavage was investigated." (PMID 29371673, 2018). "HSPCs were rescued during infection by inhibiting RIPK1 with Necrostatin-1s." (PMID 30080899, 2018). "We hypothesized that 3Cpro interacts with RIPK1 or TRIF, and thereby cleaves the death kinase RIPK1, and corrupts caspase-8 activation at late stages of infection." (PMID 29449668, 2018). "The striking increase in full length pro-caspase 8, as well as active caspase 8, in Ifnar1-/- mice was apparent prior to infection, suggesting Ifnar1-/- mice may be poised to resist RIPK1-dependent cell death." (PMID 30080899, 2018). "The in vitro addition of the HRV 3C protease to whole cell lysate resulted in the same c-terminal 23 kDa RIPK1 cleavage product, further confirming that HRV 3C is likely the viral protease responsible for cleavage of RIPK1 during HRV16 infection and this was confirmed to be the c-terminal of RIPK1." (PMID 29371673, 2018). "HRV 2A protease activity was confirmed in all infection samples, as evidenced by the virus specific cleavage of eIF4G (lanes 4–7, eIF4G blot) which did not parallel RIPK1 cleavage, eliminating 2A as the protease responsible for RIPK1 cleavage." (PMID 29371673, 2018). "Forty-eight hours after infection, we observed cleavage of RIPK1, which again could be inhibited with SQV suggesting that PR plays a key role in this event." (PMID 26297639, 2015). "M. tb infection did not stimulate phosphorylation of RIPK1 at any time point tested, but did decrease the phosphorylation elicited by the CREB inhibitor at 30 min post-infection, suggesting that M. tb may transiently inhibit early activation of RIPK1 in a CREB-independent manner." (PMID 37000865, 2023). "To determine if RIPK1 mediates MLKL phosphorylation in ZBP1-deficient astrocytes following infection, we treated ZBP1+/+ and ZBP1−/− derived astrocytes with the RIPK1 inhibitor, GSK963, during infection with the HSV-1(MacIntyre), HSV-1(F)-ICP6-RHIM Mut, and HSV-1(F) strains." (PMID 35549723, 2022). "Thus, it has been recently described that GSDME, a protein related with pyroptosis and IL-1β release, is activated in neutrophils in a RIPK1-dependent manner and that the FADD-RIPK1-caspase 8 complex is recruited after infection to cleavage GSDMD and initiates the inflammatory cell death." (PMID 35716229, 2022). "Examining changes in RIPK1 over the course of MDM infection in vitro, we found an upregulation of full length RIPK1 at day 2 post-infection until day 8 post-infection that was associated with a gradual and significant accumulation of cleaved RIPK1 on days 2, 4, 6 and 8 post-infections." (PMID 34824340, 2021). "Our findings suggest that RIPK1 activity can protract disease and RIPK1 antagonism may be therapeutically relevant for improving hematopoiesis and long-term outcomes in patients surviving acute, severe infections where type I IFNs are elevated." (PMID 30080899, 2018). "KAT2A knockdown aggravated necroptosis and upregulated phosphorylation of RIPK1, whereas RIPK1 inhibitor Nec-1 rescued SC19-induced necroptosis, indicating that KAT2A regulates RIPK1-dependent necroptosis during SC19 infection." (PMID 41882776, 2026). "The results showed that the levels of phosphorylated MLKL, RIPK1, and RIPK3, and cytotoxicity were higher in cells infected with ΔospD3 than in cells infected with WT Shigella, indicating that ΔospD3 infection triggers necroptosis." (PMID 40931196, 2025).
infection (continued). "For example, the bacterial effector OspD3, secreted by Shigella flexneri, cleaves host kinases RIPK1 and RIPK3 to evade necroptosis-mediated immune responses during infection." (PMID 40424468, 2025). "To further determine the necrotic nature of a fusogenic and non-fusogenic OV-mediated death, we analyzed the expression and phosphorylation of the necroptosis mediators, RIPK1, RIPK3, and MLKL, over the time course of infection by western blot analysis." (PMID 40896365, 2025). "RIPK1 degradation with R1-ICR-3 treatment prevented RIPK3, especially activated RIPK3 (pRIPK3), from binding to ZBP1 during HSV-1(ICP6mut) infections." (PMID 39345610, 2024). "Accordingly, infection or cellular stressors can lead to cell death by the combinatory crosstalk of pyroptotic, apoptotic, and necroptotic molecules (like ZBP1, RIPK1, RIPK3, CASP1, CASP8, and NLRP3, MLKL, and GSMDs) to effectively control pathogenic invasion." (PMID 38590437, 2024). "Cell death control in development, inflammation and infection is coordinated by RIPK1, but only a small part of the complex PTM code of RIPK1 is understood so far." (PMID 37495567, 2023). "We probed cell lysates for phosphorylated RIPK1, RIPK3 and MLKL by Western blot over a time course from 15–90 min post-infection." (PMID 37000865, 2023). "Subsequently, the phosphorylated RIPK1, RIPK3, and MLKL promoted the ROS accumulation of mitochondria and Ca2+ influx in RAW264.7 cells, further exacerbating cell necrosis and persistent infection." (PMID 37175724, 2023). "Knockdown of RIPK1, RIPK3, or MLKL in the background of infection with either RVA NCDV or DS-1 suppressed the expression of RVA proteins and titers." (PMID 34668777, 2022). "THP-1 and RAW264.7 cells were pre-treated with ZVAD-FMK (40 μM), Nec-1s (50 μM), and GSK’872 (20 nM), the inhibitors for pan-caspases, RIPK1, and RIPK3, respectively, followed by infection with ZIKV." (PMID 35446851, 2022). "This was the case for the type I IFN response, but also for RIPK1, STAT1, DDX58, ISG15, TRIM25, and MYD88, involved in TNF-, TLR-, RLR-, and NFκB signaling, 48 h after MOPV infection." (PMID 35337059, 2022). "Receptor-interacting serine/threonine-protein kinase 1 (RIPK1) is an important regulator of cell death pathways during embryogenesis and in infection/inflammation." (PMID 36329033, 2022). "RHIM-mediated signaling by RIPK1, TRIF, ZBP1, and RIPK3 culminating in necroptosis is a key pathway utilized by cells in inflammation and infection settings." (PMID 36040212, 2022). "Infection with the bovine NCDV and human DS-1 RVA strains was shown to activate receptor-interacting protein kinase 1 (RIPK1), RIPK3, and mixed-lineage kinase domain-like protein (MLKL), the key necroptosis molecules in virus-infected cells." (PMID 34668777, 2022). "A time-course analysis of DENV2 infection revealed a reduction in intracellular RIPK1 protein concomitant with the expression of DENV proteins, beginning as early as 6h post-infection." (PMID 36310878, 2022). "Enteropathogenic E. coli (EPEC) uses the type III secretion system effector EspL to degrade the RHIM‐containing proteins RIPK1, RIPK3, TRIF, and ZBP1/DAI leading to restricting necroptosis and pyroptosis during infection." (PMID 34977874, 2021). "In our study increased phosphorylation of RIPK1, RIPK3, and MKLK in ZIKV-infected astrocytes was detected early in the infection but only RIPK3 and MLKL phosphorylation remained throughout the infection and cell death." (PMID 33796483, 2021). "This suggested that in vitro infection of MDMs with HIV-1 CS204 resulted in the initial upregulation and subsequent down-regulation of full length RIPK1 and accumulation of cleaved RIPK1 over the period of HIV infection." (PMID 34824340, 2021). "RIPK1 and RIPK3 were slightly increased upon infection in the livers of uninfected and Lm-infected OTUB1FL and OTUB1LPC-KO mice." (PMID 33712742, 2021).
infection (continued). "The results indicated that RIPK1 and RIPK3 are involved in the injury process of chicken lungs after infection with P. multocida, and the mechanisms of lung injury induced by different strains are different." (PMID 32286320, 2020). "In the present study, we showed that RIPK1 and RIPK3 were upregulated in lung tissues of severe patients dying from human infection with H7N9 virus." (PMID 31080811, 2019). "In this study, the mRNA level of RIPK1 and RIPK3 was enhanced in the lung tissues of patients killed by infection with H7N9 virus (P<0.05), as well as the protein level of RIPK1 and RIPK3 (P<0.05)." (PMID 31080811, 2019). "The addition of the 3C protease inhibitor Rupintrivir led to a reduction in the c-terminal 23 kDa cleavage product seen in infection, suggesting that HRV16 3C protease is responsible for the virus-induced RIPK1 cleavage product." (PMID 29371673, 2018). "A 23 kDa RIPK1 cleavage product was observed only in samples treated with 3C protease (lanes 2, 4, 6, RIPK1 blot), suggesting that 3C protease can cleave RIPK1 giving rise to the product observed in HRV16 infection." (PMID 29371673, 2018). "Immunostaining and confocal imaging of RIPK1 and RIPK3 in sort-purified HSPCs revealed distinct IFNαR-dependent changes during IOE infection." (PMID 30080899, 2018). "There was no detectable decrease in the full-length ALIX, ACLY, hnRNP K, RIPK1, GBF1, and PFAS proteins, suggesting that only a subset of these target proteins are cleaved during infection." (PMID 29437971, 2018). "Infection with RNA viruses triggers the formation of a RIPK1/RIPK3 complex, and inhibition of RIPK1 kinase function blocked viral-induced activation of the inflammasome." (PMID 26297639, 2015). "PR-mediated proteolytic modification of RIPK1 and RIPK2 therefore likely represents an important strategy of HIV-1 to counter cellular restriction and modulate the host response to infection." (PMID 26297639, 2015). "Noteworthy, in our studies we observed the return of full-length RIPK1, RIPK2 and PARP protein levels at later time points (24 h) following infection." (PMID 22685397, 2012). "RIPK1 inhibition in DMV/1639-infected macrophages significantly reduced cell viability and increased apoptosis but did not alter necroptosis, supporting RIPK1’s critical role in apoptotic regulation during infection." (PMID 40284946, 2025). "During infection, ZBP1 responds to IAV and forms the ZBP1-RIPK3 complex, which then facilitates recruitment of RIPK1 and further forms ZBP1-PANoptosomes with ZBP1/RIPK3/RIPK1/FADD/CASP8 as the main components." (PMID 40568592, 2025). "Although the calculated fold changes for RIPK1 and RIPK3 phosphorylation were rather low and subject to high inter-experimental variation over the time course of infection, trends point toward an increased expression and phosphorylation of MLKL in rVSV-infected A549 and H1437 cells 16–24 hpi." (PMID 40896365, 2025). "Blocking necroptosis with the addition of the RIPK1 inhibitor Necrostatin-1 did not enhance the effect of QVD on infection frequency, but did result in a small increase in the frequency of successful progression to productive replication." (PMID 39093901, 2024). "Collectively, our data demonstrate that IFN-γ priming upregulates TNFR1 expression and sensitize neutrophils to release robust TNF upon infection, while LPS-IFN-γ co-priming promotes RIPK1-dependent pyroptosis by producing sufficient soluble TNF prior to infection." (PMID 38965211, 2024). "Moreover, H37Rv infection increased the expression of the molecules involved in the necroptotic pathway, such as ASK1, p-38, RIPK1, RIPK3, and caspase-8, while H37Ra increased caspase-8 and decreased RIPK3 at the transcriptional level." (PMID 35631013, 2022).
infection (continued). "In contrast, IC6 has been shown to inhibit necroptosis in human cells by impairing RIPK1-RIPK3 necrosome formation and reduction of RIPK1 autophosphorylation, suggesting that HSV-1 evolved to escape necroptosis in humans for the sake of establishing a successful infection." (PMID 35203445, 2022). "Mice lacking caspase-8, RIPK3, and RIPK1 (apoptosis/necroptosis) survived infection similarly to mice lacking either RIPK3 or MLKL, suggesting pyroptosis primarily protects against B. thailandensis in pyroptosis-competent mice." (PMID 34154417, 2021). "Similarly, siRNA‐mediated knockdown of RIPK1 or RIPK3 in HT29 cells infected with ΔospD3 decreased levels of phosphorylated MLKL and cytotoxicity to the levels observed in WT infection." (PMID 32657447, 2020). "Although the transcription of RIPK1 (a key mediator of necroptosis) was unchanged, its suppressor BIRC3 showed greater transcription in Axl−/− macrophages than in control macrophages after infection." (PMID 32611752, 2020). "Possibly, the impact of apoptosis is more predominant after inflammation and infection to worsen the IVD degeneration, and in animal disease models, the mRNA expression of RIPK1 was lower in degeneration models after 3 months, while that of TNF was significantly higher." (PMID 31029152, 2019). "Infection by some RNA viruses, including vesicular stomatitis virus (VSV), Sendai virus, and influenza virus, induces NLRP3 inflammasome activation, and the silencing of RIPK1 and RIPK3 leads to a severe reduction in inflammasome activation." (PMID 31509938, 2019). "Late in infection, we found that dsRNA colocalized with TLR3 and RIPK1 in vesicular structures." (PMID 29449668, 2018). "Whether the increased RIPK1, RIPK3 and MLKL activation marks a typical necroptotic, lytic event during infection or if KPn utilizes the necroptosis machinery to modulate cellular functions in its favor, or a combination of both, requires further investigation." (PMID 30273394, 2018). "However, during infection type I IFNs mediated HSPC death by reducing caspase 8 expression and activity, which correlated with reduced RIPK1 and RIPK3 cleavage in the BM." (PMID 30080899, 2018). "Of note, NEC-1 did not affect RIPK1 cleavage or VP2 production in QVD-treated cells and HRV-A16 infection in hAECN (data not shown), confirming the earlier finding that RIPK1 per se was dispensable for infection." (PMID 29449668, 2018). "RIPK1 antagonism with Necrostatin-1s rescued HSPC and HSC numbers during infection." (PMID 30080899, 2018). "As expected, a 23 kDa RIPK1 cleavage product was observed in samples subject to infection, but without treatment of Rupintrivir, correlating with a decrease in full length RIPK1 (lanes 4, 5 in RIPK1 blots)." (PMID 29371673, 2018). "RIPK1 was cleaved in cells infected with HRV16, however, in contrast to the 38 kDa product produced by caspase 8 cleavage, a c-terminal 23 kDa cleavage product is produced during HRV16 infection." (PMID 29371673, 2018). "The upregulation of viral cleavage of RIPK1 with caspase 8 activation was not seen in the infection models." (PMID 29371673, 2018). "Neither the RIPK1 kinase inhibitor NEC-1 nor the depletion of RIPK1 by RNAi affected the death pathways or HRV-A16 infection." (PMID 29449668, 2018). "Infection of macrophages with low MOI (MOI 3) was not able to stimulate RIPK1-dependent cell death in the presence of TNFα." (PMID 28892415, 2017). "This explains why we did not detect cleaved RIPK1 at early time points or when the later stages of infection were blocked either with RT or integrase inhibitors." (PMID 26297639, 2015). "Although EspL cleaved RIPK1 and RIPK3 to generate the expected p61 and p50 fragments, LDH release, apoptotic caspase processing and cleavage of the fluorogenic caspase substrates were comparable between C. rodentium and ΔespL infection in macrophages and CMT-93 cells." (PMID 40128366, 2025).
infection (continued). "Localized delivery of RIPK1/RIPK3/MLKL pathway inhibitors may confine necroptosis suppression to the infection site, thereby reducing local inflammation without compromising systemic immune defenses." (PMID 41142308, 2025). "Caspase-8, which is recruited and activated by auto-phosphorylated RIPK1 to drive apoptosis, was only partially cleaved and not fully processed into its active form in Rickettsia-infected cells, even during the late stages of infection." (PMID 40607949, 2025). "Interestingly, the ETI against Y. pseudotuberculosis dependent on RIPK1 kinase activity is detected in oral but not systemic mouse infection." (PMID 39883598, 2025). "In addition, even infection of macrophages with the classical RIPK1/caspase-8–activating pathogen, Yersinia pseudotuberculosis, sensitized TBK1/IKKε-inhibited cells to enhance RIPK1/caspase-8 activation and death but also enhanced secondary caspase-1 activation." (PMID 40053580, 2025). "Infection of LLC-PK cells with PSaV Cowden strain showed that the interaction of phosphorylated RIPK1 (pRIPK1) with RIPK3 (pRIPK3), mixed lineage kinase domain-like protein (pMLKL) increased in a time-dependent manner, indicating induction of PSaV-induced RIPK1-dependent necroptosis." (PMID 36735696, 2023). "However, we found that BHA did not provide protection against necroptosis that does not rely on the kinase activity of RIPK1, as observed following infection of MEFs by Herpes simplex virus 1 (HSV1)." (PMID 34262020, 2021). "However, creatinine level, WBC count, PLT count, PT, age, sex, primary infection site, microorganism identified, the type of organ dysfunction, and RIPK1 level were not correlated with fatal events." (PMID 29137405, 2017). "Nec-1s treatment does not result in an increase in lung neutrophils following Ft LVS infection, while macrophage numbers are higher at days 3 and 6 post-infection, suggesting that the early neutrophil response is restricted by Nlrp3, but not by RIPK1." (PMID 27926940, 2016). "Interestingly, the levels of the phosphorylated forms of RIPK1, RIPK3, and MLKL, the major signaling molecules in the RIPK1-dependent necroptosis pathway, were observed as early as 4 hpi and continuously increased to 20 hpi in response to infection with both RVA strains." (PMID 34668777, 2022). "In contrast to infection with ΔospD3, infection with ΔospC1ΔospD3ΔospI did not increase the levels of phosphorylated MLKL, RIPK1, and RIPK3, and cytotoxicity." (PMID 40931196, 2025). "In contrast to infection with ΔospD3, infection with ΔospD3ΔospI did not increase the levels of phosphorylated MLKL, RIPK1, and RIPK3, and cytotoxicity." (PMID 40931196, 2025). "Paradoxically, various genetic and biochemical approaches have confirmed that the RHIM not kinase activity of RIPK1 disturbs the ZBP1-RIPK3 necrosome and avoids the aberrant necroptosis in the absence of infection." (PMID 36142136, 2022). "Similar to treatment with LPS/5z7, infection of macrophages at high MOI induced cell death that was dependent on TRIF, ZBP1, and the kinase activity of RIPK1, and independent of TNFR1." (PMID 33397971, 2021). "Our observations expose that the basal FADD-CASP8 is sufficient to collaborate with the infection-driven elevation in levels of CASP8, cFLIP, and RIPK1 for unleashing extrinsic apoptosis when vICA is absent." (PMID 33126536, 2020). "Although RIPK1 and ACLY were cleaved by 3Cpro, the masses of the in vitro cleavage products were not similar to those produced during infection." (PMID 29437971, 2018). "Blocking RIPK1 signaling using Nec-1s during acute IOE infection rescued HSPC and HSC depletion in IOE infection, though it did not improve survival." (PMID 30080899, 2018). "Interestingly, by day 7 of infection, multiple genes were elevated in young H1N1 infected lung, such as Atg5, Mapk8, Tbk1, Casp8, and Ripk1, that were not similarly expressed in response to H3N2." (PMID 34829979, 2021).